FUCA2 (alpha-L-fucosidase 2)
Description:
Alpha-L-fucosidase is responsible for hydrolyzing the alpha-1,6-linked fucose joined to the reducing-end N-acetylglucosamine of the carbohydrate moieties of glycoproteins.
Synonyms: MGC1314; dJ20N2.5
Tractability: Small molecule: it belongs to a druggable protein family. Antibody: UniProt places it where antibodies can reach, with high confidence; its Gene Ontology location is reachable by antibodies, with high confidence; UniProt predicts a signal peptide or a membrane-spanning region. PROTAC: ubiquitination databases record sites on it; its protein half-life has been measured; a small molecule that binds it is known.
Target class: Enzyme; Hydrolase
Gene: Protein-coding gene on chromosome 6 (143,493,961 to 143,511,842, reverse strand). Ensembl gene ENSG00000001036.
Subcellular location: Secreted
Pathways (Reactome):
Metabolism of proteins: Post-translational protein phosphorylation; Regulation of Insulin-like Growth Factor (IGF) transport and uptake by Insulin-like Growth Factor Binding Proteins (IGFBPs)
Immune System: Neutrophil degranulation
Gene Ontology:
Molecular function: alpha-L-fucosidase activity; protein binding
Biological process: fucose metabolic process; glycoside catabolic process; regulation of entry of bacterium into host cell; response to bacterium; carbohydrate metabolic process
Cellular component: extracellular exosome; extracellular region; azurophil granule lumen; endoplasmic reticulum lumen; lysosome
Genetic constraint (gnomAD): Loss-of-function variants: 36 observed, 46.85 expected, observed/expected ratio (o/e) 0.77, 90% interval 0.59 to 1.01. The upper end of that interval is the gene's LOEUF score, 1.01, which puts it in group 4 of 6, group 1 being the genes least tolerant of losing a copy. Missense variants: 472 observed, 535.1 expected, observed/expected ratio (o/e) 0.88, 90% interval 0.82 to 0.95. Synonymous variants: 198 observed, 195.99 expected, observed/expected ratio (o/e) 1.01, 90% interval 0.9 to 1.14.
Homologues: Orthologues: chimpanzee FUCA2 (99% identical), macaque FUCA2 (97% identical), pig FUCA2 (86% identical), dog FUCA2 (83% identical), rabbit FUCA2 (82% identical), rat Fuca2 (81% identical), mouse Fuca2 (81% identical), guinea pig FUCA2 (79% identical), tropical clawed frog fuca2 (67% identical), zebrafish fuca2 (62% identical), Drosophila melanogaster Fuca (49% identical), Caenorhabditis elegans W03G11.3 (46% identical). Paralogues in human: FUCA1 (54% identical).
Diseases named in the same sentence as FUCA2 in open-access papers:
FUCA2 is named in the same sentence as 31 diseases in open-access papers, as found by Europe PMC text mining. Sharing a sentence is not in itself a finding about the gene and the disease. The quoted sentences say what the papers report.
fucosidosis (3 papers, 2016 to 2025). "Since FUCA1-deficient fucosidosis patients exhibit, in addition to the accumulation of many fucosylated glycoconjugates, massive storage of Lewis X and H antigen-glycolipids in tissues and urine, it is rather unlikely that FUCA2 has a hydrolytic activity towards these substrates." (PMID 40940767, 2025). "Interestingly, neither fucosidosis patients nor animal models of this disease show quantifiable amounts of residual fucosidase activity, although a second lysosomal fucosidase, initially named plasma α-L-fucosidase (FUCA2; NCBI NP_114409), has been reported." (PMID 40940767, 2025).
hepatocellular carcinoma (3 papers, 2014 to 2021). A malignant tumor that arises from hepatocytes. "Previous studies have shown that FUCA2 is a diagnostic marker in hepatocellular carcinoma and gastric cancer." (PMID 34745134, 2021). "Interestingly, FUCA2 has been implicated as a factor associated with several neoplastic diseases including endometrial, oral, gastric, and hepatocellular carcinoma." (PMID 24454818, 2014).
gastric cancer (2 papers, 2021 to 2024). A primary or metastatic malignant neoplasm involving the stomach. "Alpha-L-fucosidase 2 (FUCA2) is an essential catalytic factor in the fucosylation of gastric cancer cells, and FUCA2 fucosidase activity is associated with tumor formation, metastasis inhibition, and multi-drug resistance." (PMID 38406279, 2024). "In addition, FUCA2 was found showed diagnostic and therapeutic value in helicobacter pylori-infected gastric cancer." (PMID 34745134, 2021). "Immunohistochemistry has revealed that FUCA2 expression is significantly increased in gastric cancer tissues, and FUCA2 expression levels are correlated with surgical stage and advanced histological grade." (PMID 38406279, 2024).
lung carcinoma (2 papers, 2021 to 2023). "To prove the oncogene role of FUCA2, we performed the experimental verification in lung cancer cells." (PMID 34745134, 2021). "In addition, MTT assays was also conducted to validate the oncogene role of FUCA2 in lung cancer cells." (PMID 34745134, 2021). "We found that the inhibition of FUCA2 could significantly reduce the proliferation rate of lung cancer cell lines A549 and NCI-H1299, which was consistent with our conclusion." (PMID 34745134, 2021). "Then, MTT assay showed that the inhibition of FUCA2 could significantly reduce the cell viability of lung cancer cell lines A549 and NCI-H1299, which was consistent with our conclusion." (PMID 34745134, 2021). "FUCA2 knockdown inhibited the cell viability in lung cancer cells." (PMID 34745134, 2021).
sickle cell disease (2 papers, 2016 to 2020). Sickle cell anemias are chronic hemolytic diseases that may induce three types of acute accidents: severe anemia, severe bacterial infections, and ischemic vasoocclusive accidents (VOA) caused by sickle-shaped red blood cells obstructing small blood vessels and capillaries. "Genome-wide analyses have identified FUCA2 and IL-18 as novel genes associated with diastolic function in African Americans with sickle cell disease." (PMID 32475352, 2020).
breast carcinoma (1 paper, 2024). "Anti-FUCA2 antibodies inhibit the proliferation of breast cancer cells, and this is reversed by ectopic expression of FUCA2, suggesting that this fucosidase has oncogenic potential." (PMID 39123480, 2024).
colorectal cancer (1 paper, 2023). A primary or metastatic malignant neoplasm that affects the colon or rectum. "Although this is the first time ADAT2 has been linked to colorectal cancer, our data and literature information make ADAT2 (as well as FUCA2.rs11155297) interesting candidates for future studies in colorectal cancer progression and prognosis." (PMID 36998434, 2023). "Also, while neither TMED7 (transmembrane p24 trafficking protein 7) nor FUCA2 (alpha-L-fucosidase 2) genes are known to be linked to colorectal cancer, FUCA2 is associated with various cancers, tumor microenvironment and prognostic features." (PMID 36998434, 2023).
epilepsy (1 paper, 2023). A brain disorder characterized by episodes of abnormally increased neuronal discharge resulting in transient episodes of sensory or motor neurological dysfunction, or psychic dysfunction. "In the epilepsy vs. control comparison, only one protein (FUCA2) was elevated with many trending proteins in this heterogeneous disease group." (PMID 37521285, 2023). "For epilepsy vs. control, the differentially expressed protein FUCA2 (alpha-L-fucosidase 2) was increased by 2.5-fold (p = 1.17 x 10−5)." (PMID 37521285, 2023). "In epilepsy vs. control, there were no pathways associated with the one altered protein FUCA2." (PMID 37521285, 2023).
inflammatory bowel disease (1 paper, 2025). A spectrum of small and large bowel inflammatory diseases of unknown etiology. "PheWAS analysis unveiled significant associations between FUCA2 and multiple immunopathological phenotypes, with particularly notable positive correlations observed in rheumatoid arthritis and inflammatory bowel disease." (PMID 40822862, 2025).
lysosomal storage disorders (1 paper, 2024). "Plasma alpha-L-fucosidase (FUCA2) is a hydrolase that plays a key role in the pathogenesis of glycoprotein lysosomal storage disorders." (PMID 38982370, 2024).
ocular melanoma (1 paper, 2021). A melanoma that arises from the structures of the eye or ocular adnexa. "Analysis of genetic alterations in FUCA2 using cBioPortal revealed that the highest frequency of alteration in this gene (>8%) occurred in patients with ocular melanoma with “deep deletion” as the primary type." (PMID 34745134, 2021).
pancreatic adenocarcinoma (1 paper, 2014). "Alternatively, the activity of an induced host fucosidase could make free fucose available for C. jejuni similar as described for the human fucosidase FUCA2 of cultured human gastric and pancreatic adenocarcinoma cells upon infection with Helicobacter pylori." (PMID 25325018, 2014).
Sjögren syndrome (1 paper, 2024). "Low plasma FUCA2 levels were observed in patients with chronic autoimmune disorders, such as Sjögren syndrome." (PMID 38982370, 2024).
type 1 diabetes (1 paper, 2024). "High urinary FUCA2 levels were observed in pediatric patients with type 1 diabetes." (PMID 38982370, 2024).
uveal melanoma (1 paper, 2021). A melanoma derived from melanocytes of the uveal tract. "Results revealed that high FUCA2 level was significantly linked to worse OS in patients with BRCA (p= 0.001), CESC (p=0.023), GBM (p=0.014), KICH (p= 0.020), LGG (p<0.001), LIHC (p<0.001), LUAD (p<0.001), MESO (p = 0.011), and Uveal Melanoma (UVM) (p = 0.008)." (PMID 34745134, 2021).
tumor (11 papers, 2014 to 2025). "High level of FUCA2 expression may contribute to increased infiltration of tumor-associated macrophages and associate with an immunosuppressive microenvironment in pan-cancer." (PMID 37256139, 2023). "The expression of alpha-l-fucosidase 2 (FUCA2) was significantly elevated in GC tissues compared with non-tumoral tissues and was associated with TNM III and IV and advanced histological grade tumor states." (PMID 40821120, 2025). "FUCA2 mediates the adhesion between Helicobacter pylori and gastric mucosa and is upregulated in 24 tumor types." (PMID 36046653, 2022). "Beyond that, we found significant correlations among FUCA1/FUCA2 expression and pathological grade, pathological stage, postoperative residual tumor numbers, and primary therapeutic effect." (PMID 34881177, 2021). "The Kyoto Encyclopedia of Genes and Genomes (KEGG) analysis illustrated that FUCA1/FUCA2 exerted tumor-suppressive function by regulating the glycosylation." (PMID 34881177, 2021). "FUCA2, an α‐L‐fucosidase, has been reported to promote tumor cell invasion." (PMID 41355397, 2025). "Both heterozygous and homozygous CNV analyses showed significant amplification for DCAF13 and FAM83D and deletion for FUCA2, UQCRH, and NDC80 in tumor samples." (PMID 41355397, 2025). "UNG, FUCA2, DERA, GMFB, TF, and SNX24 as significantly downregulated upon mir-145 over-expression, are expected to have elevated expressions in tumor samples considering low levels of miR-145 in several cancer types." (PMID 27655328, 2016).
cancer (8 papers, 2016 to 2024). A tumor composed of atypical neoplastic, often pleomorphic cells that invade other tissues. "In contrast, FUCA2 is proposed to be a cancer prognostic marker due to its high mRNA expression in pan-cancer patients and association with poor survival rates." (PMID 39123480, 2024). "Moreover, recent study reveals that FUCA2 is also a diagnostic and prognostic biomarker a therapeutic target in pan-cancer." (PMID 36046653, 2022). "Finally, our GSEA and GSVA results indicated that FUCA2 was linked to pathways involved in immune regulation in pan-cancer." (PMID 34745134, 2021). "Additionally, FUCA2 was negatively associated with CD8+ T cells in several cancers." (PMID 34745134, 2021). "The correlation between FUCA2 high expression and cancer has also been confirmed at the protein level in lung carcinoma and uterine corpus endometrial carcinoma." (PMID 39123480, 2024). "Herein, a comprehensive analysis of the FUCA2 function was carried out using multi-omics datasets for 33 cancers from the TCGA database, and further explored the link between FUCA2 level and the TIME." (PMID 34745134, 2021). "Next, we assessed the correlations between immune cell infiltration and FUCA2 expression in 33 cancers using a published work and the ImmuCellAI database." (PMID 34745134, 2021). "We then generated Kaplan–Meier curves to ascertain the prognostic value of FUCA2 promoter methylation in TCGA pan-cancer dataset." (PMID 34745134, 2021). "For example, We found that FUCA2 was over-expressed in most cancers and indicated a worse prognosis for several types of tumors, while FUCA2 was down-expressed and predicted a better prognosis for KIRC." (PMID 34745134, 2021). "We used Cox proportional hazards model to elucidate the relationship of FUCA2 level with overall survival (OS) of patients in TCGA pan-cancer." (PMID 34745134, 2021). "In conclusion, our study suggested an oncogenic effect of FUCA2 and its potential as a prognostic biomarker in pan-cancer." (PMID 34745134, 2021). "Our study reveals that FUCA2 is a potential oncogene and is indicative biomarker of a worse prognosis in pan-cancer." (PMID 34745134, 2021). "In the present study, we used three different methods to assess how FUCA2 levels correlate with infiltrating immune cells in pan-cancer, and obtained similar results." (PMID 34745134, 2021). "Next, gene alteration, clinical characteristics and prognostic values of FUCA2 were elucidated based on TCGA pan-cancer data." (PMID 34745134, 2021). "In contrast, FUCA2 expression is commonly elevated in cancer." (PMID 39123480, 2024). "Furthermore, FUCA2, a fucosidase, is upregulated in most tumors and predicts poor overall survival in pan-cancer, including LUAD." (PMID 37256139, 2023). "Collectively, the obtained results indicate that FUCA2 may be a potential target for future development of cancer therapies." (PMID 34745134, 2021). "Besides, cycle-related pathways (such as “Cell Cycle”, “Apoptosis”, and “AKT signaling”) are closely related to FUCA2 in pan-cancer." (PMID 34745134, 2021). "Further, FUCA2 expression was closely correlated with DNA methylation, and a high FUCA2 methylation level could serve as a biomarker of prognosis in patients with several cancers." (PMID 34745134, 2021). "Therefore, pan-cancer analysis for identifying differential expressions and the role of FUCA2 in various tumors is clinical valuable." (PMID 34745134, 2021). "For GSVA results of 50 hallmark pathways from the MSigDB, we found that FUCA2 was associated with many cancer-promoting and immune-related pathway, including Glycolysis, PI3K AKT MTOR signaling, TGF BETA signaling, interferon alpha and interferon gamma response in pan-cancer." (PMID 34745134, 2021). "As we have found that FUCA2 has a potential cancer-promoting effect in pan-cancer, including LUAD, we further performed the experimental verification of FUCA2 in LUAD to prove its oncogene role." (PMID 34745134, 2021).
cancer (continued). "To elucidate the potential biological pathways regulated by FUCA2, we conducted GSEA using “clusterprofiler” in pan-cancer subjects, then selected the 12 tumors with similar results." (PMID 34745134, 2021). "We identified six genes including UNG, FUCA2, DERA, GMFB, TF, and SNX24 as significantly downregulated and two genes including MYL9 and TAGLN as significantly upregulated upon mir-145 over-expression in distinct cancer types." (PMID 27655328, 2016). "Moreover, FUCA2 level showed a positive relationship with most immunosuppression genes, including programmed death-ligand 1 (PD-L1), transforming growth factor beta 1 (TGFB1), and interleukin-10 (IL10) in most cancer types." (PMID 34745134, 2021).
FUCA2 also shares sentences with these, for which no sentence is quoted: atherosclerosis (1 paper); benign breast tumors (1); bladder cancer (1); fibrosarcoma (1); glioblastoma (1); head and neck squamous cell carcinoma (1); immune disease (1); infection (1); Jaundice (1); lung adenocarcinoma (1); Pan (1); periodontitis (1); prostate carcinoma (1); rheumatoid arthritis (1).